TNF (tumor necrosis factor)
Diseases named in the same sentence as TNF in open-access papers (continued):
Sharing a sentence is not in itself a finding about the gene and the disease.
Sepsis (continued). "In vitro studies have shown that the anti-inflammatory cytokine interleukin 10 (IL-10) is a regulatory factor that blocks TNF-α, IL-1β, and IL-8 and many studies have found higher concentrations of IL-10 in patients with sepsis." (PMID 33997001, 2021). "An increase in the number and activity of immunosuppressive neutrophils has been established during sepsis and under the influence of such stimuli as LPS and TNF." (PMID 34136120, 2021). "Although persistent platelet activation is most often related to septicemia, a few studies have shown that platelet aggregation is decreased in experimental sepsis, possibly signalled via the TNF pathway." (PMID 35052592, 2021). "In a sepsis model using lipopolysaccharide (LPS), injection of the N-glycan upregulated serum IL-10, and suppressed pro-inflammatory IL-1β, TNF-α and IFN-γ." (PMID 33727664, 2021). "The mutant displayed sustained release of IL-6 compared to TNF-α during co-culturing with A549 lung cell lines, attenuation in mice sepsis model, and significantly reduced ability to adhere to and invade A549 lung cells and form biofilms on abiotic surfaces." (PMID 34950110, 2021). "It was found that sepsis-induced myocardial injury significantly promoted the release of TNF-α, IL-6, and IL-8 and decreased the IL-10 level, compared with that in the sham group." (PMID 33819192, 2021). "We then identified inflammation in the mice with sepsis myocardial injury, and the levels of TNF-α, IL-6, IL-8, and IL-10 were evaluated using ELISA." (PMID 33819192, 2021). "In sepsis patients, regarding inflammatory cytokines, JKAP level negatively associated with TNF-α (P = 0.008), IL-1β (P = 0.009), and IL-17 (P = 0.003) expressions." (PMID 33083958, 2021). "Cecal ligation and puncture (CLP)-induced sepsis in obese mice results in increased expression of pro-inflammatory cytokines (TNF-α and IL-6) in visceral WAT and decreased circulating adiponectin levels." (PMID 34322037, 2021). "IL-6 and TNF-α are released by the activated neutrophils and macrophages, and are well recognized as pro-inflammatory cytokines and biomarkers for the diagnosis of sepsis." (PMID 34721017, 2021). "In the present study, upregulation of both TNF-α and IL-1β, the most extensively studied cytokines in sepsis pathophysiology, was noted in the liver, heart and lung tissues of rats in the S group, consistent with previous reports from other researchers." (PMID 34499695, 2021). "In another CLP-induced polymicrobial sepsis model, EA downregulated the level of TNF-α, IL-6, nitrite, and high-mobility group box 1 (HMGB-1) in serum, and reduced nuclear fraction NF-κB p65 activity in the spleen." (PMID 35095910, 2021). "Previous studies showed that TNF-α and IL-1β produced by macrophages activated neutrophils during sepsis, and high concentrations of TNF-α and IL-1β have been reported in BALF from ARDS patients." (PMID 34641966, 2021). "Extracting the pattern of the cytokines in the patients with sepsis, we found that TNF-α has a bi-modal distribution, having either very high or very low levels (data not shown)." (PMID 34819932, 2021). "MiR-93-5p was reported to be downregulated in LPS-treated HK2 cells, and participated in sepsis-induced AKI via KDM6B/H3K27me3/TNF-α axis." (PMID 33468219, 2021). "Increased efflux of nitrogen and amino acid from skeletal muscle and loss of body protein have been shown in mice administered with TNFα and in pathological conditions characterized by elevated endogenous TNFα like cancer or experimental sepsis." (PMID 33525436, 2021). "In 2000, it was discovered in a rat sepsis model created by lipopolysaccharide administration that direct electrical stimulation of the vagal efferent tract suppressed the production of TNF-α (an inflammatory cytokine) and, consequently, shock." (PMID 33877485, 2021).
Sepsis (continued). "Although specific immunomodulatory therapy targeting inflammatory cytokines has been confirmed in sepsis models, clinical trials on the blockade of TNF, IL-1, and other cytokines failed." (PMID 34759282, 2021). "A number of studies have reported that an excessive productions of TNF-α, IL-6, and IL-8 severely enhances myocardial dysfunction during sepsis." (PMID 33819192, 2021). "The protein and mRNA expressions of IL-1β, IL-6, and TNF-α were all markedly elevated in renal tissue of mice with CLP-induced sepsis, which were consistent with findings from other studies." (PMID 34187277, 2021). "In one clinical trial, recombinant GM-CSF therapy in immunosuppressed pediatric patients with sepsis restored tumor necrosis factor production in lymphocytes and reduced nosocomial infections to zero in the treatment group." (PMID 33920518, 2021). "High chloride fluids have also been shown in experimental sepsis models to increase TNF, IL-10, and IL-6 concentrations and to impair microcirculatory function compared to balanced crystalloids." (PMID 33718468, 2021). "The intestinal epithelial cell (IEC)-derived luminal EVs during sepsis inhibit the release of pro-inflammatory cytokines TNF- α and IL-17a through autocrine and paracrine." (PMID 33995102, 2021). "Numerous factors during surgery, including organ damage, sepsis, release of tumor necrosis factor in cancer surgery, metabolic status, and the stress response, accelerate the release of MYO, which confuses the biochemical picture." (PMID 34646835, 2021). "Most works focusing on these ncRNAs are related to micro RNAs (miRNAs) regulating pathways crucial in sepsis pathophysiology, such as NF-ĸB, and TNF-α." (PMID 34680414, 2021). "Some of the most studied pro-inflammatory cytokines in the pathophysiology of sepsis are interleukin-1β (IL-1β) and tumor necrosis factor α (TNF-α), both released from activated macrophages." (PMID 33632243, 2021). "Similar to the observations in the pituitary gland, mRNA levels of the pro-inflammatory cytokine TNF-α were higher than normal only in the acute phase of sepsis-induced critical illness (1-day group) (p < 0.0001)." (PMID 33593393, 2021). "In our study, TNF-a levels were higher in patients who deteriorated compared to those who improved only in the groups of patients with trauma/surgery and sepsis with sufficient (AUROC 0.76) and poor (AUROC 0.66) predictive value, respectively." (PMID 33917002, 2021). "In EV71 infection, severely infected patients (including brainstem encephalitis, neurogenic pulmonary oedema, and sepsis) showed significantly higher TNF-α than those with mild infection indicating involvement of TNF-α in disease severity." (PMID 34493781, 2021). "TRAF6 is closely related to ALI caused by sepsis, and overexpression of TRAF6 increases the expression levels of TNF-α and IL-6." (PMID 34602057, 2021). "We suggest that the reduction in the dendritic cells’ proportions, along with their stunted maturation after tamoxifen treatment, produced a reduction in TNF-α and iNOS production, minimizing their deleterious effects in sepsis situations." (PMID 34073235, 2021). "In a neonatal murine E. coli sepsis model, IL-27Rα-/- mice showed lower levels of TNF-α, IL-1β and IL-6, and improved survival rates." (PMID 34079555, 2021). "GM-CSF and TNF-α were extracted as the most important cytokines for distinguishing FMF from sepsis (mean decrease accuracy 14.7 and 9.7, respectively)." (PMID 34654467, 2021). "LPS is a known stimulator in the systemic inflammatory mechanism of sepsis, LPS-triggered ROS generation, and the release of inflammatory cytokines, such as IL-1β, TNF-α, IL-6, and IL-10." (PMID 33986684, 2021). "A study shows that Scr and BUN levels, apoptotic cell scores, TNF-α and IL-1β levels, and oxidative stress are raised as well as survival rates and renal histology scores are declined in the sepsis-induced AKI30." (PMID 33785732, 2021).
Sepsis (continued). "In experiments using a sepsis mouse model, it was found that the spleen contributed to the production of TNF-α, and splenectomy diminished the effect of vagus nerve stimulation (VNS)." (PMID 33877485, 2021). "Sepsis also up-regulates the inflammatory cytokines TNF-α, IL-6 and HMGB1 in BV-2 microglia cultures and animals." (PMID 34711216, 2021). "TNFα-induced systemic inflammatory response syndrome (SIRS) is an animal model of sepsis, which involves both RIPK1-dependent apoptosis and necroptosis." (PMID 34075030, 2021). "It was reported moderate increase in TNFα concentration in brain of mice 6 h after induction of sepsis and that increase was higher 12 h up to 7 days after induction." (PMID 33608025, 2021). "It is therefore plausible that KYNA and its derivatives inhibit NET formation during sepsis through the inhibition of TNF-α and HMGB1 release and IL-1β activation." (PMID 34475875, 2021). "Many experiments have shown that Era, an inhibitor of ferroptosis, can relieve sepsis induced by CLP or LPS in mice, which is associated with a reduced level of inflammatory cytokines such as tumor necrosis factor (TNF)-α, IL-1β, and HMGB1." (PMID 34482365, 2021). "In sepsis, experimental and clinical studies have shown that TNF-α is produced in large amounts, but only during the first hours after bacterial exposure." (PMID 33439360, 2021). "In fact, it was observed reduced TNFα circulatory concentration after concomitant 21 nm cit-AuNP and antibiotic injection 18 h after induction of sepsis in mice compared to mice with sepsis that received only antibiotic treatment." (PMID 33608025, 2021). "Some clinical studies investigating the monoclonal antibodies produced against TNFα in patients with sepsis or septic shock have been reported." (PMID 34921186, 2021). "Because TNF from M1-polarized macrophages is crucial for septic shock, we induced sepsis in Zc3h12c+/+/Zc3h12c−/− and Zc3h12cfl/fl/Zc3h12cMΦΔ mice with LPS." (PMID 34215755, 2021). "While tumor necrosis factor α and interleukin 1β are released early during sepsis, HMGB1 is a late mediator expressed only after about 24 h and remains at elevated levels before death occurs." (PMID 33658363, 2021). "The activation of NF-κB participates in the occurrence and development of sepsis by enhancing the transcription of various proinflammatory cytokines, including TNF-α, IL-6, and IL-1β." (PMID 34721636, 2021). "NF-κB participates in the development of sepsis by enhancing the transcription of proinflammatory cytokines, such as TNF-α, IL-6, and IL-1β." (PMID 34616305, 2021). "In these studies, RIC reduced the levels the proinflammatory cytokines TNF-α, IL-1β, and IL-6, as well as suppressing the sepsis-induced increase in plasma cardiac troponin I." (PMID 34169381, 2021). "The risk predictive value of the levels of sIL-2R, TNF-α, and PCT for sepsis was assessed using binary logistic regression analysis, with median cutoff points (two classifications) and quartiles (P25, P50, and P75) as cutoff points (four classifications)." (PMID 34745113, 2021). "Sepsis-induced innate immune suppression is typically occult but can be identified by quantifying production of tumor necrosis factor (TNF)α, an inflammatory cytokine, in whole blood after stimulation with lipopolysaccharide (LPS)." (PMID 34659221, 2021). "The parameters commonly used to monitor inflammation process and sepsis evolution are lactate, C-reactive protein, procalcitonin, and, more recently, TNF, IL-1beta, and IL-6." (PMID 33685484, 2021). "Pellino1−/− mice suppressed the protein expression of Pellino1, TRAF6 and NF-κB and inhibited the levels of TNF-α, IL-6, IL-1β and IL-18 in mice of sepsis." (PMID 33632252, 2021). "The results showed that at 6 h after sepsis, except for IL-6, TNF-α, IL-1β, and IL-10 levels decreased in DEX-treated mice." (PMID 33981237, 2021).
Sepsis (continued). "In rats, BER inhibits increasing TNF-α and IL-6 levels induced by multimicrobial sepsis in the intestinal mucosal barrier and increases the level of tight junction proteins and permeability of epithelial cells." (PMID 34712727, 2021). "Numerous studies demonstrated that the excessive release of proinflammatory cytokines, such as IL-1β, IL-6, and TNF-α, triggered the pathophysiological abnormities of sepsis and played prominent roles in septic AKI." (PMID 33511217, 2021). "The mechanism of sCD40L in sepsis is as follows: The type I transmembrane receptor protein belongs to the Tumor Necrosis Factor (TNF) receptor superfamily." (PMID 34178892, 2021). "We found that LPS-induced sepsis elicited increased the serum level and mRNA expression of TNF-α and IL-6 in cardiac tissues." (PMID 35005242, 2021). "Overproduction of inflammatory cytokines including tumor necrosis factor (TNF)-α, interleukin (IL)-1α, IL-1β, and IL-6 also leads to cardiac dysfunction in sepsis." (PMID 34035183, 2021). "The production of TNF‐α has been demonstrated to be indicative of sepsis in mice following LPS administration and in HL‐1 cells following LPS treatment." (PMID 33369167, 2021). "The MSCs on the SF nanofibers significantly reduced plasma IL-6 and TNF-α levels, which were increased by polymicrobial sepsis induction within 24 h." (PMID 33946773, 2021). "Conversely, B-1a cells also produce IL-3, IL-17, and TNF-α, which exhibit pro-inflammatory roles in sepsis." (PMID 33708213, 2021). "In clinical research, TNF-α was considered as the initial factor that triggered and mediated the sepsis." (PMID 33967760, 2021). "Binary logistic regression analysis was used to evaluate the risk predictive value of the levels of sIL-2R, TNF-α, and PCT in the sepsis group." (PMID 34745113, 2021). "The levels of the proinflammatory cytokines TNF-α, IL-1β, IL-6, IL-12p70, and IL-10 in the serum and in the lungs of the A. baumannii-derived sepsis mouse model treated with IOX1 were significantly reduced." (PMID 33536477, 2021). "Several studies have evaluated the potential of anti-TNF therapies with in-vivo sepsis models, highlighting how early administration can increase survival." (PMID 34439967, 2021). "Multiple studies have shown that the levels of inflammation-related factors in serum are directly proportional to the severity of sepsis, such as TNF-α, IL-6, and IL-1β." (PMID 33710444, 2021). "At the molecular level, silencing lncRNA HOTAIR improved heart function in LPS-induced sepsis mice, and markedly decreased TNF-α production by activating NF-κB pathway, involving phosphorylation of NF-κB p65 subunit, in LPS-induced HL-1 cells." (PMID 34055659, 2021). "We reported earlier on the central role of intact GR signaling LPS-induced acute lung injury, TNF-α-induced systemic inflammation and cecal ligation, and puncture-induced sepsis." (PMID 35011674, 2021). "We also observed that administering IL-38 to mice with CLP-induced sepsis lowered the circulating concentrations of the proinflammatory cytokines IL-1β, IL-6, and TNF-α, while elevating systemic levels of the anti-inflammatory cytokine IL-10." (PMID 34955683, 2021). "Infection group Y (sepsis group = 1, infection group = 0) was used as the dependent variable; sIL-2R(X1), TNF-α(X2), and PCT(X3) were used as the independent variables." (PMID 34745113, 2021). "The early phase of sepsis is characterized by excessive inflammation with the manifestation of systemically boosted production of pro-inflammatory cytokines, including TNF-α, IL-6 and IL-1β." (PMID 33842398, 2021). "Inflammatory pathways and reactive oxygen/nitrogen species synthesis or metabolism are critically important in liver tissue during sepsis, since oxidative liver damage can further initiate production of TNFα, interleukins, and chemokines by immune cells." (PMID 33471430, 2021).
Sepsis (continued). "The mechanism of sepsis-induced hypocalcemia remains unknown; however, this appears to be associated with elevated levels of proinflammatory cytokines, such as tumor necrosis factor (TNF)-α, interleukin (IL)-1, IL-6; hypoparathyroidism, vitamin D deficiency, or resistance." (PMID 34680835, 2021). "Previous reports have revealed that the exposure to LPS combined with TNF‐α mimics the stressful condition accounting for liver inflammatory response and liver injury in sepsis." (PMID 33982381, 2021). "In-vitro decreased T-cell apoptosis, potentiated monocytic LPS-induced TNF-α and IL-6 production from sepsis patients." (PMID 33920518, 2021). "In our study, the animals with sepsis developed proinflammatory profiles that were characterized by increased expression of IL-1β, IL-10, IL-6 and TNF-α." (PMID 33676566, 2021). "The cytokines IL-1β, IL-6, and TNF-α mediate the immunopathological features of sepsis and are released by neutrophils to exacerbate acute inflammation." (PMID 33588861, 2021). "It is “a late mediator of sepsis” with postponed release in comparison with “early mediators of sepsis” represented, e.g., by TNF-α." (PMID 34439812, 2021). "During the development of sepsis, several inflammatory cytokines, including IL-1, TNF-α, and IL-6, are released and thus initiate downstream pathways that lead to cell death and organ disorder." (PMID 32892306, 2021). "IL-18, a cytokine upstream of the inflammatory cascade reaction, induces the massive synthesis of inflammatory cytokines (TNF, IL-1β), which are the key mediators of sepsis-induced organ injury." (PMID 35054259, 2021). "TNF-α plays a central role in the pathogenesis of sepsis and is an early regulator of the immune response." (PMID 34641966, 2021). "TNF tolerance can help address hyper- or chronic inflammatory diseases such as sepsis, but excessive tolerance can lead to immune paralysis in sepsis." (PMID 34829825, 2021). "Several reports have demonstrated that TNF-α, IL-6, and IL-10 can serve as both makers and mediators of sepsis severity and that elevated cytokine levels predict mortality following CLP." (PMID 35003518, 2021). "The relationship between sepsis and increased levels of proinflammatory cytokines such as TNF-α and IL-1β is known as a mechanism for eliminating invading pathogens." (PMID 34499695, 2021). "TNF-α, IL-6, IL-12 and IL-1β play an important role in sepsis, and levels of TNF-α are negatively correlated with survival in septic patients." (PMID 33995024, 2021). "On the other hand, the enormous activation of proinflammatory cytokines and the increase in the circulating levels of tumor necrosis factor (TNF)-alpha and interleukin (IL)-6 contribute to sepsis-related organ failure." (PMID 35052907, 2021). "It has been shown that increased pro-inflammatory cytokine levels such as TNFα and IL-6 levels correlate with poor outcome in sepsis; however, their routine clinical utility remains questionable." (PMID 34830673, 2021). "Among the 152 KEGG pathways, 8 pathways were reported to be associated with sepsis and were reported as cytokine–cytokine receptor interaction and some signaling pathways of JAK-STAT, TLR, NF-κB, T-cell receptor, PI3K-Akt, TNF, and IL-17." (PMID 34938184, 2021). "A meta-analysis in 2013 showed a modest reduction in death in sepsis in patients given anti-TNF medications but concluded that larger trials with over 10,000 patients were needed to fully demonstrate this benefit." (PMID 34485339, 2021). "Another advantage of PCT is that its serum concentrations remain high compared to other sepsis biomarkers such as tumor necrosis factor-alpha (TNFa) and IL-6, making PCT more useful in predicting infection severity and responsiveness to treatment." (PMID 34912626, 2021).